ACE (angiotensin I converting enzyme)
Diseases named in the same sentence as ACE in open-access papers (continued):
Sharing a sentence is not in itself a finding about the gene and the disease.
autism (4 papers, 2015 to 2023). Persistent deficits in social interaction and communication and interaction as well as a markedly restricted repertoire of activity and interest as well as repetitive patterns of behavior. "While previous research has linked genetic variations in ACE to autism, this study is the first to examine the role of the Yin/Yang arms of RAS in in utero VPA-exposed animals." (PMID 38137376, 2023). "The novel findings of our study are the significant association of two polymorphisms, [ACE (I/D and rs4343)] located on ACE gene, with autism." (PMID 27082637, 2016). "There were strong associations between both DD genotype of ACE I/D and the D allele, with autism (P = 0.006, OR = 2.9, 95% CI = 1.64–5.13 and P = 0.006, OR = 2.18, 95% CI = 1.37–3.48 respectively)." (PMID 27082637, 2016). "Considering the relation between the three polymorphisms of ACE (I/D, rs4343 and rs4291) with the level of ACE activity, we have investigated this association with autism, in a case-control study." (PMID 27082637, 2016). "The increased ACE activity may then explain the observed association of the mentioned polymorphisms with autism in our population." (PMID 27082637, 2016). "Another finding was the significant associations of DD genotype of ACE with autism." (PMID 27082637, 2016). "One hundred and twenty children with a diagnosis of autism were molecularly genotyped for ACE I/D and two SNPs within the ACE gene (rs4291 and rs4343)." (PMID 27082637, 2016). "The importance of renin-angiotensin system (RAS) elements in cognition and behavior besides the interaction of angiotensin II (Ang II), the main product of angiotensin-converting enzyme (ACE), with neurotransmitters in CNS, especially dopamine, proposes the involvement of RAS in autism." (PMID 27082637, 2016).
autonomic neuropathy (4 papers, 2013 to 2020). An inherited or acquired peripheral neuropathy affecting the autonomic nervous system. "In the present era of evidence‐based therapies, for the majority of cardiac amyloid patients, particularly those with restrictive cardiac physiology and autonomic neuropathy, the use of β‐blockers or ACE inhibitors for the treatment of HF is proscribed." (PMID 23537813, 2013).
bipolar disorder (4 papers, 2015 to 2024). A disorder of the brain that causes unusual shifts in mood, energy, activity levels and the ability to carry out day-to-day tasks. "Candidate gene studies suggested a potential role for polymorphisms in angiotensin converting enzyme (ACE) in bipolar disorder." (PMID 32356562, 2020). "While the extant evidence is not yet strong enough to support the routine use of medications used for the treatment of CVRFs to target psychiatric symptomatology in bipolar disorder, there are some interesting findings related to statins and ACE inhibitors that invite rigorous clinical trials." (PMID 32356562, 2020).
bronchopulmonary dysplasia (4 papers, 2004 to 2021). Bronchopulmonary dysplasia is a chronic respiratory disease that results from complications related to lung injury during the treatment of infant acute respiratory distress syndrome in low-birth-weight premature infants or from abnormal lung development in older infants. "Other risk factors include low birth weight, congenital diaphragmatic hernia, bronchopulmonary dysplasia, and maternal nephrotoxic medications exposure like Angiotensin-Converting Enzyme (ACE) inhibitors." (PMID 33981652, 2021).
cerebral infarction (4 papers, 2017 to 2025). An ischemic condition of the brain, producing a persistent focal neurological deficit in the area of distribution of the cerebral arteries. "Building on these findings, we also explored the potential effects of other commonly prescribed cardiovascular medications, such as beta blockers and ACE inhibitors, on functional outcomes and cerebral infarction." (PMID 41298953, 2025). "However, in contrast, a previous study from Catto and colleagues found that serum ACE activity were markedly reduced during the acute phase of cerebral infarction." (PMID 29228591, 2017). "l-borneol can also inhibit neuronal apoptosis and enhance the stability of neovascularization by inhibiting the levels of ACE, MMP9, HIF1α, TGF-β1 and Tie2, thereby improving the neurological deficit in ischemic rats, reducing the rate of cerebral infarction, and exerting neuroprotective effects." (PMID 33746762, 2021). "ACE is the rate-limiting enzyme of RAS, and regulates conversion of inactive Ang I to active Ang II, thereby participating in pathogenesis of several neurological disorders including cerebral infarction." (PMID 29228591, 2017).
coagulopathies (4 papers, 2014 to 2023). "Previous research has shown that MLT can induce the release of bradykinin (BK) in association with angiotensin-converting enzyme (ACE) dysfunction, thus leading to the inhibition of platelet aggregation, coagulation disorders and fibrinolysis." (PMID 38017537, 2023). "Functional SNPs in these genes and their action may be exaggerated by coagulopathies (ACE, AGT) or by apoptosis (STAT1)." (PMID 25264875, 2014).
colon adenocarcinoma (4 papers, 2005 to 2026). "Substance P is another substrate cleaved by ACE, which is involved in stimulating pro-inflammatory cytokine production and binds the NK-1 receptor, found on colon adenocarcinoma cells, to facilitate cell proliferation and migration of tumour cells." (PMID 41085561, 2026). "Their profiles were investigated in NTS1R-positive colon adenocarcinoma WiDr cells and mice treated or not with the neprilysin (NEP)-inhibitor phosphoramidon (PA) and/or the angiotensin converting enzyme (ACE)-inhibitor lisinopril (Lis)." (PMID 32526874, 2020).
Crohn disease (4 papers, 2007 to 2024). A gastrointestinal disorder characterized by chronic inflammation involving all layers of the intestinal wall, noncaseating granulomas affecting the intestinal wall and regional lymph nodes, and transmural fibrosis. "In both cohorts, we found that the expression of ileal ACE mRNA is reduced in Crohn’s disease in comparison with healthy controls and that ileal ACE2 mRNA expression negatively correlates with the tissue expression of IFN-γ." (PMID 35406751, 2022).
diastolic heart failure (4 papers, 2010 to 2019). Heart failure caused by abnormal myocardial relaxation during diastole leading to defective cardiac filling. "ACE DD and AT1R 1166 CC genotypes have been linked with a greater risk of diastolic heart failure." (PMID 22333273, 2012).
dystrophinopathies (4 papers, 2019 to 2024). "The identification of an active ACE-tRNA for arginine in muscle is relevant for the treatment of dystrophinopathies caused by nonsense mutations." (PMID 30778053, 2019).
endometrial cancer (4 papers, 2022 to 2025). Primary or metastatic malignant neoplasm involving the endometrium (mucous membrane that lines the endometrial cavity). "ACE gene polymorphism may be associated with the pathogenesis of endometrial cancer, and may be related to the development of the disease as well as the age of onset." (PMID 36619582, 2022). "It should be noted that in a previous study, we found an association between the prevalence of endometrial cancer and single nucleotide polymorphisms (SNPs) associated with increased expression of AT1R (rs5186) and ACE (rs4291 and rs4292)." (PMID 41303450, 2025). "We also showed that the mRNA expression of AGTR1 and ACE were significantly higher in endometrial cancer tissue, further indicating the potential for increased Ang II/AT1R signalling in endometrial cancer." (PMID 41303450, 2025). "In addition, perindoprilat, an ACE inhibitor, did not have any effect on the viability of any of the three endometrial cancer lines." (PMID 41303450, 2025).
enteropathy (4 papers, 2017 to 2025). "The aim of this study is to assess the risk of enteropathy associated with ARBs and angiotensin converting enzyme inhibitors (ACE‐i) by using data from large administrative and claim databases." (PMID 29457309, 2018). "However, limited epidemiological studies compared enteropathy outcomes between olmesartan and other anti-hypertensive medications, including other ARBs and ACE inhibitors, and results have been mixed." (PMID 31217979, 2019). "However, limited epidemiological studies compared enteropathy outcomes between olmesartan and other anti-hypertensive medications, including other ARBs and angiotensin-converting enzyme (ACE) inhibitors, and results have been mixed." (PMID 31217979, 2019). "Inducing enteropathy, three types of medications were used: indomethacin, an NSAID (35 mg/kg); methotrexate, an antitumor drug (10 mg/kg); and enalapril, an ACE inhibitor (2 mg/kg/day)." (PMID 29064425, 2017).
gestational diabetes (4 papers, 2009 to 2024). Carbohydrate intolerance first diagnosed during pregnancy. "Studies had previously correlated these polymorphisms, especially the I/D polymorphism of the ACE gene, with T2DM even in Indian women with gestational diabetes." (PMID 29694640, 2018).
Hyperinsulinemia (4 papers, 2009 to 2025). An increased concentration of insulin in the blood. "ACE and NOS3 are associated with inflammation, hyperinsulinism, and metabolic diseases." (PMID 19208189, 2009).
Hypomagnesemia (4 papers, 2021 to 2025). An abnormally decreased magnesium concentration in the blood. "Hypomagnesemia is frequently associated with the use of drugs such as aminoglycosides, cyclosporine, cisplatin, amphotericin B, ACE inhibitors, proton pump inhibitors, and some diuretics (thiazides and loop)." (PMID 34574074, 2021).
intracerebral haemorrhage (4 papers, 2008 to 2024). "It was also found that ACE rs4646994 DD genotype was associated with higher risk for primary spontaneous intracerebral haemorrhage patients." (PMID 28336767, 2017). "A total of 8 studies (744 cases and 1289 controls) were identified that evaluated the ACE/ID polymorphism of which five related to intracerebral haemorrhage, one for subarachnoid haemorrhage and two for ruptured intracranial aneurysm." (PMID 19008959, 2008).
kidney stone (4 papers, 2018 to 2023). "To further validate the ameliorative role of FMT in kidney stone-induced damage in hyperoxaluric rats, we performed immunohistochemical staining to evaluate the protein levels of renin, ACE, and OPN." (PMID 37313343, 2023).
liver failure (4 papers, 2021 to 2024). A liver disease characterized by the liver losing or has lost all of its function. "Firstly, it was considered responsible for liver failure; the use of angiotensin II receptor blockers and ACE inhibitors can cause liver failure." (PMID 37185723, 2023).
lung squamous cell carcinoma (4 papers, 2022 to 2026). "Among the hyper-altered cancer types, uterine corpus endometrial carcinoma, skin cutaneous melanoma, and lung squamous cell carcinoma were the most prominent cancer types, which was probably due to the high mutation frequencies of INSR, ACE, and NOS3." (PMID 35513851, 2022). "Collectively, these results highlight ACE and HSPB8 as promising targets for lung squamous cell carcinoma treatment." (PMID 41490177, 2026).
memory impairment (4 papers, 2012 to 2025). "Furthermore, it has been reported that memory impairment induced by streptozotocin (STZ) or amyloid beta was associated with increased ACE activity in brain." (PMID 23008812, 2012). "At this point, the translational approach suggesting convergence to memory impairments with higher ACE activity levels reinforce our findings, although with some cautions." (PMID 26645626, 2015). "A number of preclinical studies attempted to explore the role of ACE in memory function using experimental models of memory impairment." (PMID 23008812, 2012). "Recently it has been reported that chronic administration of ACE inhibitor ameliorated streptozotocin and scopolamine induced memory impairment by reducing cholinergic dysfunction and oxidative stress." (PMID 23008812, 2012). "The present study showed that treatment with perindopril ameliorated colchicine-induced memory impairment in mice implicating central ACE in memory function." (PMID 23008812, 2012). "Inhibition of ACE was also found to ameliorate cerebral hypoperfusion and amyloid beta induced memory impairment in rodents." (PMID 23008812, 2012). "The present study investigated the involvement of central ACE in colchicine-induced memory impairment in the context of cholinergic function and oxidative stress." (PMID 23008812, 2012). "Therefore, the present study explored the role of central ACE by utilizing intracerebral (IC) colchicine-induced model of memory impairment in mice." (PMID 23008812, 2012). "The present study showed that angiotensin converting enzyme (ACE) plays a crucial role in memory deficit induced by intracerebral (IC) colchicine because treatment with perindopril, an ACE inhibitor, prevented memory impairment, oxidative stress and cholinergic dysfunction in mice." (PMID 23008812, 2012). "Notably, the BBB-permeable angiotensin converting enzyme (ACE) inhibitor, captopril, or the angiotensin-receptor blocker (ARB), telmisartan, have shown efficacy in counteracting this microglia-mediated synaptic pruning, reversing the DNRab-induced memory impairment." (PMID 41013206, 2025).
metabolic dysfunction-associated steatotic liver disease (4 papers, 2016 to 2025). Metabolic dysfunction-associated steatotic liver disease (MASLD, formerly known as nonalcoholic fatty liver disease or NAFLD) is a type of liver disease that is not caused by alcohol. "Tekatas DD, Bahcecioglu IH, Ispiroglu M, Sahin A, Ilhan N, Yalniz M, Demirel U. Role of Renin–Angiotensin-converting Enzyme Level and ACE Gene Polymorphism in Patients with Nonalcoholic Fatty Liver Disease." (PMID 29201746, 2016). "In this study, we aimed to investigate the histological and clinical effect of angiotensin-converting enzyme (ACE) and ACE gene polymorphism in nonalcoholic fatty liver disease (NAFLD) and their roles in the progression of the disease." (PMID 29201746, 2016). "The classical axis of renin-angiotensin system (RAS), angiotensin (Ang)-converting enzyme (ACE)/Ang II/AT1, contributes to the development of non-alcoholic fatty liver disease (NAFLD)." (PMID 26883384, 2016).
Myelopathy (4 papers, 2018 to 2025). Myelopathy is an descriptive term, referring to pathology leading to a neurologic deficit related to the spinal cord. "As an example, administration of ACE-inhibitor after irradiation has been reported to mitigate radiation-induced myelopathy in healthy central nervous system tissue." (PMID 33789720, 2021). "Within a pilot trial, we used the ACE-inhibitor ramiprilTM to test the impact on radiation-induced myelopathy after carbon ion and photon irradiation." (PMID 29325596, 2018). "For the ACE-inhibitor ramiprilTM, a mitigative rather than protective effect was found, however, the design of targeted protective drugs requires more detailed knowledge on the molecular pathways during the pathogenesis of radiation-induced myelopathy." (PMID 29325596, 2018).
polycystic ovary syndrome (4 papers, 2009 to 2024). A disorder that manifests as multiple cysts on the ovaries. "Additionally, some research suggests that the D allele of the ACE gene is associated with the formation of polycystic ovary and hyperandrogenism." (PMID 32604999, 2020).
Pompe disease (4 papers, 2013 to 2021). "Thus we decided to evaluate if also in Pompe’s disease the different ACE polymorphism could modulate the final phenotype of the disease." (PMID 25103075, 2014). "We demonstrate that ACE and ACTN3 polymorphisms are genetic factors able to modulate the clinical phenotype of patients affected with Pompe disease." (PMID 25103075, 2014). "While the pro-fibrotic polymorphism in LTBP4 found in the DBA2/J background has not been implicated in Pompe disease, polymorphisms in angiotensin-converting enzyme (ACE) and alpha-actinin 3 (ACTN3) impact disease onset within LOPD." (PMID 34778273, 2021). "Similar to other lysosomal storage disorders, genetic, epigenetic, and environmental factor including race, ethnicity, gender, and polymorphisms in other genes (angiotensin-converting enzyme (ACE), alpha-actinin-3 (ACTN3)) have been suggested to affect the onset and progression of Pompe disease." (PMID 32932790, 2020).
Pruritus (4 papers, 2010 to 2021). Pruritus is an itch or a sensation that makes a person want to scratch. "Cardiovascular drugs were associated with generally higher rates of pruritus, with similar rates among ACE inhibitors (0.69%), beta-blockers (0.75%), hydrochlorothiazide (0.68%), amiodarone (0.62%), and statins (0.67%)." (PMID 31382689, 2019). "Among cardiovascular drugs, calcium channel blockers, beta blockers, and hydrochlorothiazide are associated with pruritus from skin inflammation, while itch with ACE inhibitors is thought to result from increased levels of bradykinin." (PMID 31382689, 2019).
renal cell carcinoma (4 papers, 2011 to 2025). "Similarly, patients with high ACE expression in renal cell carcinoma may benefit more from specific polyphenols, which exhibit strong ACE inhibitory activity, such as rosmarinic acid (IC50 = 0.05 μmol/L)." (PMID 41301459, 2025). "For instance, in clear cell renal cell carcinoma (CC-RCC), there is a notable increase in the levels of renin and angiotensin-converting enzyme (ACE), a phenomenon also observed in other cancers such as reninoma, where renin levels exceed those found in normal tissues." (PMID 41301459, 2025).
Respiratory tract infection (4 papers, 2013 to 2023). An infection of the upper or lower respiratory tract. "synthesize proteins that are ACE inhibitors, with a potential for downgrading the severity of inflammation in patients with respiratory tract infections." (PMID 34684384, 2021).
restrictive cardiomyopathy (4 papers, 2024 to 2025). A type of heart disorder referring to the inability of the ventricles to fill with blood because the myocardium (heart muscle) stiffens and looses its flexibility. "Symptomatic management, including diuretics, ACE inhibitors, and spironolactone, was commonly prescribed for most DCM and restrictive cardiomyopathy (RCM) patients." (PMID 38568384, 2024).
rhabdomyolysis (4 papers, 2019 to 2024). Necrosis or disintegration of skeletal muscle often followed by myoglobinuria. "Interestingly, overdoses with beta-blockers, calcium-channel inhibitors, acetaminophen, colchicine, lithium, angiotensin-converting enzyme (ACE) and inhibitors/angiotensin II-receptor-blockers were significantly associated with an increased risk of AKI in our poisoned patients with rhabdomyolysis." (PMID 32998294, 2020).